ZNF73P (zinc finger protein 73, pseudogene)
Synonyms: hZNF2; Cos12; ZNF186; ZNF2; ZNF73
Gene: Unprocessed pseudogene on chromosome 22 (11,474,744 to 11,479,643, forward strand). Ensembl gene ENSG00000288262.
Diseases named in the same sentence as ZNF73P in open-access papers:
ZNF73P is named in the same sentence as 1 disease in open-access papers, as found by Europe PMC text mining. Sharing a sentence is not in itself a finding about the gene and the disease.
ZNF73P shares sentences with these, for which no sentence is quoted: esophageal cancer (1 paper).